IGFBP7 (insulin like growth factor binding protein 7)
Diseases named in the same sentence as IGFBP7 in open-access papers (continued):
Sharing a sentence is not in itself a finding about the gene and the disease.
chronic kidney disease (10 papers, 2013 to 2025). Impairment of the renal function secondary to chronic kidney damage persisting for three or more months. "In individuals with MM, serum transgelin, U IGFBP-7/creatinine and U TIMP2/creatinine ratios may have utility as biomarkers of predicting advanced chronic kidney disease stages." (PMID 38708150, 2024). "This prospective observational study aimed to validate and measure TIMP‐2 and IGFBP7 in urine of dogs and to compare these values between healthy dogs, dogs with AKI, dogs with chronic kidney disease (CKD) and critically ill (CI) dogs." (PMID 38053473, 2023). "We also examined the performance of urine [TIMP-2]·[IGFBP7] compared to various other markers including urine KIM-1 and urine NGAL in terms of discrimination between AKI of different severities and various non-AKI conditions including chronic kidney disease." (PMID 23388612, 2013).
bladder cancer (8 papers, 2014 to 2024). "IGFBP7, purified from the conditioned medium from bladder carcinoma cells, stimulated fibronectin and α-smooth muscle actin (α-SMA) synthesis in normal fibroblasts, as well as promoted fibroblast proliferation and migration." (PMID 39045455, 2024). "Although IGFBP7 expression has previously been proposed as a serum biomarker for bladder cancers, whether methylation-dependent mechanisms also regulate IGFBP7 expression in MPM, and to the extent its serum levels could be a useful biomarker in MPM have yet to be addressed." (PMID 24690739, 2014). "When isolated from conditioned medium of human bladder carcinoma cells and coated on cell culture plates, IGFBP7 did not stimulate the growth or migration of HUVECs, but enhanced their efficient adhesion." (PMID 39045455, 2024).
cardiac hypertrophy (8 papers, 2017 to 2024). "Confirming this, systematic proteomic research places IGFBP-7 as a biomarker involved in cardiac hypertrophy and HF." (PMID 39335666, 2024). "In diabetic patients, the level of IGFBP-7 is positively correlated with increased collagen accumulation, fibrosis processes, and myocardial hypertrophy." (PMID 39335666, 2024). "In addition, EVO preserves mitochondrial function by increasing the activity of the PGC1α/NRF1/TFAM signaling pathway and inhibits the development of cardiac hypertrophy and fibrosis by attenuating TGFβ/IGFBP7/Col1a1 expression." (PMID 37009790, 2023). "Cardiotrophin-1, activin A, insulin-like growth factor binding protein-7 (IGFBP-7) and Heart fatty-acid binding protein have demonstrated a stable positive correlation with cardiac hypertrophy, contractibility and steatosis responses." (PMID 28231848, 2017).
thyroid cancer (8 papers, 2015 to 2024). "To reveal the mechanism underlying the anti-proliferative effect of IGFBP7 on thyroid cancer, we analyzed the expression levels of cell cycle regulators." (PMID 31183073, 2019). "In vivo experiments revealed that ectopic IGFBP7 expression markedly suppressed growth of tumor xenografts derived from these thyroid cancer cell lines, while IGFBP7 silencing accelerated tumor growth." (PMID 31183073, 2019). "Taken together, our findings suggest that IGFBP7 plays an important tumor-suppressive role in human thyroid cancer, especially in FTC and ATC subtypes and may represent a promising biomarker and therapeutic target for the disease." (PMID 31183073, 2019). "In parallel, the various thyroid cancer tissues collected in our study showed loss of IGFBP7 expression regardless of BRAF status." (PMID 31183073, 2019). "IGFBP7 might act as a tumor suppressor by inhibiting the proliferation of thyroid cancer cells via the downregulation of the activity of AKT, leading to an increase in the expression of the cell cycle inhibitors p27Kip1 and p21Cip1." (PMID 31183073, 2019). "The kinase activity assay demonstrated that silencing of IGFBP7 in various thyroid cancer cells markedly promoted, whereas overexpression of IGFBP7 suppressed, endogenous AKT activity, as demonstrated by the phosphorylation levels of a common AKT substrate, GSK3β." (PMID 31183073, 2019). "Next, we assessed whether IGFBP7 inhibits growth of thyroid cancer cell-derived tumors using subcutaneous xenografts." (PMID 31183073, 2019). "However, the expression pattern of IGFBP7 and its biological function in various types of thyroid carcinoma remain poorly understood." (PMID 31183073, 2019). "For example, STAT3 was found as a negative regulator of thyroid cancer since it could activate transcription of the tumor suppressor insulin-like growth factor binding protein 7 (IGFBP7), and negatively regulate aerobic glycolysis." (PMID 27577070, 2016). "Moreover, overexpression of IGFBP7 potently suppresses, and silencing of IGFBP7 accelerates proliferation and tumor growth of both ATC and FTC cell lines, suggesting the important role for the loss of IGFBP7 expression during thyroid cancer development and progression." (PMID 31183073, 2019). "Additionally, the opposite results were observed in IGFBP7-silenced cells, indicating that IGFBP7 might inhibit cell- cycle progression in thyroid cancer cells." (PMID 31183073, 2019). "Collectively, our data suggest that IGFBP7 suppresses proliferation through the inhibition of both phosphorylation activation and kinase activity of AKT in thyroid cancer." (PMID 31183073, 2019). "As expected, overexpression of IGFBP7 markedly reduced the phosphorylation of AKT (Ser473 and Thr308) in various thyroid cancer cells, whereas silencing of IGFBP7 enhanced AKT phosphorylation (Ser473 and Thr308), indicating that IGFBP7 suppresses phosphorylation-mediated activation of AKT." (PMID 31183073, 2019). "Taken together, these data suggest that IGFBP7 strongly suppresses the growth of ATC and FTC cell-derived tumors in vivo and that IGFBP7 represents a potent tumor suppressor preventing the development and progression of thyroid cancer." (PMID 31183073, 2019). "Acting as a cell cycle repressor, IGFBP7 plays an important tumor-suppressive role in human thyroid cancer, especially in FTC and ATC subtypes and may represent a promising biomarker and therapeutic target for human thyroid cancer treatment." (PMID 31183073, 2019). "Therefore, whether and how IGFBP7 inhibits the AKT signaling pathway to upregulate the expression of p27Kip1 and p21Cip1 in thyroid cancer requires further investigation." (PMID 31183073, 2019). "However, we detected the phosphorylated levels of MEK and ERK in thyroid cancer cells with overexpression or knockdown of IGFBP7 and found that IGFBP7 did not impact on the BRAF-MEK-ERK pathway (data not shown)." (PMID 31183073, 2019).
thyroid cancer (continued). "However, the expression pattern of IGFBP7 and its biological function in various types of thyroid carcinoma have not been clearly elucidated." (PMID 31183073, 2019).
esophageal squamous cell carcinoma (7 papers, 2014 to 2025). Esophageal squamous cell carcinoma (ESCC) is a type of esophageal carcinoma (EC) that can affect any part of the esophagus, but is usually located in the upper or middle third. "Other study has shown that increased IGFBP7 also may remodel the tumor microenvironment and promote the progression of esophageal squamous cell carcinoma by activating the transforming growth factor-β1/SMAD signaling pathway." (PMID 37304887, 2023). "Moreover, in our previous study, we have conveyed that serum IGFBP7 has the potential of early diagnosis for esophageal squamous cell carcinoma and esophagogastric junction adenocarcinoma." (PMID 37304887, 2023). "In addition, TGF-β1 was found to be upregulated by IGFBP7 in esophageal squamous cell carcinoma." (PMID 41312374, 2025). "IGFBP7 signaling are often associated with cell growth suppression, and elevated expression of SULF1 has also been shown to inhibit HBEGF-dependent co-receptor functions of cell surface heparan sulfate proteoglycans (HSPGs) in hepatic and esophageal squamous cell cancer cells." (PMID 24690739, 2014). "In esophageal squamous cell carcinoma, ADAR2 is reduced in tumors, and its overexpression induces apoptosis via editing and stabilizing insulin-like growth factor-binding protein 7 (IGFBP7), inhibiting Akt signaling." (PMID 41169479, 2025). "By editing and stabilizing insulin-like growth factor binding protein 7 (IGFBP7), ADARB1 overexpression suppressed tumor growth and induced apoptosis in esophageal squamous cell carcinoma." (PMID 31491024, 2019).
liver cancer (7 papers, 2010 to 2024). An epithelial or non-epithelial malignant neoplasm that arises from the liver. "We also observed associations between 131 proteins and risk of liver cancer that included IGFBP7 and IGFBP3 [1.65 (1.48–1.84) and 0.46 (0.39–0.54), respectively], and 51 proteins and risk of kidney cancer, such as HAVCR1 and ESM1 [2.88 (2.55–3.24) and 1.84 (1.55–2.19)]." (PMID 38750076, 2024). "The study of IGFBP7 in a variety of cancers, including breast, thyroid, lung, prostate, colorectal, gastric, pancreatic and liver cancer has suggested a role of a tumour suppressor gene." (PMID 25886299, 2015). "A plasmid coding for shRNA against IGFBP7 was transfected in other liver cancer cell lines (HLE and Hep3B)." (PMID 20407444, 2010). "In addition, activation of the insulin-like growth factor (IGF) signaling pathway leads to tumorigenesis in a variety of cancers, including liver cancer, and insulin-like growth factor binding protein 7 (IGFBP7) induces cancer-specific cellular senescence by inhibiting this signaling pathway." (PMID 36950520, 2023).
multiple myeloma (7 papers, 2015 to 2025). "Conversely, higher IGFBP7 expression is associated with a lower probability of myeloma bone disease." (PMID 25887188, 2015). "Maintained expression of IGFBP7 in myeloma cells represents a novel prognostic marker linked to prognostically adverse chromosomal aberrations and a specific epigenetic profile." (PMID 25887188, 2015). "This suggests that IGFBP7 represents a novel marker of high-risk myeloma, defined by an epigenetic signature and regulated by MMSET." (PMID 25887188, 2015). "IGFBP7 has been implicated as a tumor suppressor and it may protect against bone disease in patients with multiple myeloma and promote osteogenesis of MSCs through the Wnt/β-catenin pathway." (PMID 35462909, 2022). "Moreover, we show that, in clinical myeloma samples, IGFBP7 expression is associated with higher myeloma cell proliferation, in turn associated with adverse prognosis." (PMID 25887188, 2015). "Nevertheless, the overall diagnostic performance of IGFBP-7 and TIMP-2 remains consistent across studies, underscoring their reliability as biomarkers for renal dysfunction in multiple myeloma." (PMID 40369504, 2025). "As a tumor suppressor, IGFBP7 can protect patients against bone disease in cases of multiple myeloma and overcome activin A-induced osteoblast suppression along with promoting osteogenesis in vitro." (PMID 35462909, 2022). "To address this question, we analysed the BMP antagonist expression profile in myeloma, identifying insulin like growth factor binding protein 7 (IGFBP7) as a potential gene of interest." (PMID 25887188, 2015). "The phenotype of MMSET expressing myeloma seems to overrule the weak inhibitory activity of IGFBP7 on myeloma cell proliferation." (PMID 25887188, 2015). "When IGFBP7 expression levels in whole BM samples of myeloma patients were compared with those of healthy donors, significantly lower levels in the MM samples were likewise found (P = 0.012)." (PMID 25887188, 2015). "Our results suggest that the downregulation of IGFBP7 in the myeloma microenvironment enables activin A to release its full destructive potential." (PMID 25887188, 2015). "To investigate the association between PVR expression, serum amylase, IGFBP-7, and TIMP-2 with the survival outcomes of multiple myeloma (MM) patients, we analyzed the overall survival (OS) and progression-free survival (PFS) in relation to PVR expression status." (PMID 40369504, 2025). "IGFBP-7 may antagonize the inhibitory effects on myeloma survival promoted by bone morphogenetic proteins, which may provide a rationale for its relationship with tumor load and symptomatic disease." (PMID 34946293, 2021). "Insulin-like growth factor binding protein 7 (IGFBP7) expression is associated with the poor prognosis with the absence of myeloma bone disease." (PMID 26108343, 2015). "This study demonstrates the diagnostic and prognostic value of PVR (gene expression and serum protein levels), serum amylase, and urinary biomarkers (IGFBP-7 and TIMP-2) in multiple myeloma (MM)." (PMID 40369504, 2025). "The high serum amylase, IGFBP7/creatinine, and TIMP2/creatinine levels observed in cases (p<0.001 for all) point to metabolic and renal disruptions, which are key complications in myeloma." (PMID 40369504, 2025). "The study’s objective was to evaluate the utility of urinary IGFBP-7, urinary TIMP-2, and serum transgelin levels as biomarkers for the prediction of renal impairment in patents with multiple myeloma." (PMID 38708150, 2024). "To validate these results, we analysed the promoter methylation status of IGFBP7 in a “low” (KMS-12-BM) and “high” (OPM-2) expressing MM cell line as well as in CD138 purified cells of four myeloma patients." (PMID 25887188, 2015). "The utility of the IGFBP-7 and TIMP-2 assay in multiple myeloma is unknown, and our findings serve as a preliminary report on their relationship with renal impairment." (PMID 34946293, 2021).
multiple myeloma (continued). "Possibly, the lack of IGFBP7 in the microenvironment is aggravated by low or absent intrinsic expression of IGFBP7 in myeloma cells." (PMID 25887188, 2015). "In this study we identified IGFBP7, a secreted factor with BMP antagonistic activity, and binding sites for IGF-1, insulin, VEGFA and activin A as a potential novel player in the pathogenesis of MM, including myeloma bone disease." (PMID 25887188, 2015). "Median IGFBP7 expression levels, although IGFBP7 displayed a heterogenous expression profile, were found to be downregulated in malignant plasma cells compared to their normal counterparts, suggesting that myeloma cells do not rely on the BMP antagonistic activity of IGFBP7." (PMID 25887188, 2015). "In contrast, in myeloma cases with high IGFBP7 expression the downregulation of this molecule in the microenvironment might be counterbalanced by production in myeloma cells, possibly explaining the correlation of higher intrinsic IGFBP7 expression and absence of advanced bone disease." (PMID 25887188, 2015).
ovarian carcinoma (7 papers, 2013 to 2026). A malignant neoplasm originating from the surface ovarian epithelium. "Among the potential MGL ligands, we identified glycoproteins that are linked to ovarian cancer progression, such as IGFBP7, MUC16, and VCAN, suggesting that MGL expressed by DCs may exert its immunoregulatory role by interacting with distinct cellular and matrix components." (PMID 33019700, 2020). "Further validation with serums showed statistical significance in VEGFA and IGFBP7 levels among groups of patients with ovarian cancers, benign tumors, and control groups." (PMID 24349832, 2013). "In addition, high expression of AFT3 and CXCL1 showed worse prognosis in ovarian cancer, while IGFBP7 behaved as a protective predictor according to multivariable analysis." (PMID 38395907, 2024). "However, no scientific reports on the expression and biological functions of IGFBP7 in ovarian cancer are currently available." (PMID 24349832, 2013). "Our findings combined with dysregulation in a genetic modified ovarian cancer cell line model rendered non-tumourigenic which resulted in the up-regulation of IGFBP7, supports a role in tumour suppressor pathways." (PMID 25886299, 2015). "Insulin-like growth factor binding protein 7 (IGFBP7) has been suggested to act as a tumour suppressor gene in various human cancers, yet its role in epithelial ovarian cancer (EOC) has not yet been investigated." (PMID 25886299, 2015). "Bioinformatic analysis results show that IGFBP7 is closely correlated with VEGFA protein, but no scientific reports on IGFBP7 and ovarian cancer are currently available." (PMID 24349832, 2013). "In addition, levels of IGFBP7, PAI-1, lamin B1, P21, P27, P62, p-H2AX, and other factors related to cell senescence were significantly elevated, indicating that S1PR1 may be involved in regulating ovarian cancer senescence." (PMID 37828220, 2023).
Stroke (7 papers, 2012 to 2025). Sudden impairment of blood flow to a part of the brain due to occlusion or rupture of an artery to the brain. "We have also discovered that patients who died or had MACE (MI or stroke) during 6 months of follow-up, had statistically higher IGFBP-7 concentrations, than the survivors." (PMID 35625639, 2022). "Our studies also suggest that the new “stroke genes” Fnbl5, Fndc1, Pcolce, Scpep1, and Igfbp7 induce EC-lumen formation by increasing the stiffness of the ECM and increasing BV elasticity." (PMID 24672479, 2014). "Moreover, patients who died or had MACE (MI or stroke) during 6 months of follow-up, had statistically higher IGFBP-7 concentrations than the survivors, although to confirm these reports, a larger cohort of patients and long-term follow-up would be needed." (PMID 35625639, 2022). "An age-specific effect was seen for Igfbp7 which was decreased by 2.5 fold in aged rats at day 14 post-stroke vs young rats and Pdpn (podoplanin) which was in contrast, increased by 2.5 fold increased in aged rats at day 14 post-stroke." (PMID 23251410, 2012). "The increased expression of IGFBP7 is observed in the vasculature of different brain pathological conditions, such as stroke, traumatic brain injury, or multiple sclerosis, suggesting that IGFBP7 may be a general marker of the vascular response to pathological conditions in the brain." (PMID 36079709, 2022).
acute myeloid leukemia (6 papers, 2015 to 2024). Acute myeloid leukemia (AML) is a group of neoplasms arising from precursor cells committed to the myeloid cell-line differentiation. "In acute myeloid leukemia cells, IGFBP7 cooperates with chemotherapy to induce cell cycle arrest and apoptosis and this mechanism is independent of ERK and AKT activation." (PMID 25886299, 2015). "It was also discovered that recombinant human insulin-like growth factor-binding protein 7 (rhIGFBP7) triggers the ATRA-driven eradication of leukemia stem/progenitor cells in acute myeloid leukemia (AML) with elevated retinoic acid receptor α gene (RARA) expression." (PMID 38671875, 2024). "In leukemia, IGFBP7 was reported to be co-expressed with the negative prognostic factor brain and acute leukemia, cytoplasmic (BAALC) in T-ALL and acute myeloid leukemia (AML) patients." (PMID 26450156, 2015).
breast tumor (6 papers, 2010 to 2024). "IGFBP7 was reported to suppress breast tumor growth through the induction of apoptosis and senescence pathways." (PMID 38435998, 2024). "Seth and his co-workers discovered that insulin-like growth factor binding protein 7 (IGFBP7) was down-regulated only in metastatic breast tumours." (PMID 25525461, 2014). "While Igfbp7 has been shown to decrease breast tumor growth, its role in regulating the normal mammary gland development has not been studied." (PMID 24505323, 2014). "Using copy-number and sequencing data of a large cohort of 171 breast tumours (38 metastasized, 130 no-metastasis) we observed an increased frequency of losses in those tumours that metastasized for many of the top ranked genes including BCL2 (18% vs 13%), IGFBP7 (11% vs 6%), IGF1 (8% vs 2%)." (PMID 20673354, 2010).